MIR4474 (microRNA 4474)
Synonyms: hsa-mir-4474
Gene: MicroRNA gene on chromosome 9 (20,502,265 to 20,502,342, reverse strand). Ensembl gene ENSG00000264941.
Homologues: Orthologues: chimpanzee MIR4474 (100% identical).